ARFGAP2 (ARF GTPase activating protein 2)
Description:
GTPase-activating protein (GAP) for ADP ribosylation factor 1 (ARF1). Implicated in coatomer-mediated protein transport between the Golgi complex and the endoplasmic reticulum. Hydrolysis of ARF1-bound GTP may lead to dissociation of coatomer from Golgi-derived membranes to allow fusion with target membranes.
Synonyms: ZNF289; Nbla10535; IRZ; Zfp289; FLJ14576
Tractability: Antibody: UniProt places it where antibodies can reach, with high confidence; its Gene Ontology location is reachable by antibodies, with high confidence. PROTAC: ubiquitination databases record sites on it; its protein half-life has been measured.
Gene: Protein-coding gene on chromosome 11 (47,164,299 to 47,177,474, reverse strand). Ensembl gene ENSG00000149182.
Subcellular location: Cytoplasm; Golgi apparatus membrane
Subcellular location (Human Protein Atlas): Golgi apparatus
Pathways (Reactome):
Vesicle-mediated transport: COPI-dependent Golgi-to-ER retrograde traffic; COPI-mediated anterograde transport
Signal Transduction: CDC42 GTPase cycle
Gene Ontology:
Molecular function: channel activator activity; GTPase activator activity
Biological process: COPI coating of Golgi vesicle; positive regulation of cytokine production; retrograde vesicle-mediated transport, Golgi to endoplasmic reticulum
Cellular component: Golgi apparatus; Golgi membrane; cytosol; cytoplasm
Genetic constraint (gnomAD): Loss-of-function variants: 43 observed, 69.27 expected, observed/expected ratio (o/e) 0.62, 90% interval 0.49 to 0.8. The upper end of that interval is the gene's LOEUF score, 0.8, which puts it in group 3 of 6, group 1 being the genes least tolerant of losing a copy. Missense variants: 621 observed, 681.81 expected, observed/expected ratio (o/e) 0.91, 90% interval 0.85 to 0.97. Synonymous variants: 244 observed, 251.5 expected, observed/expected ratio (o/e) 0.97, 90% interval 0.87 to 1.08.
Homologues: Orthologues: chimpanzee ARFGAP2 (99% identical), macaque ARFGAP2 (99% identical), pig ARFGAP2 (96% identical), guinea pig ARFGAP2 (94% identical), dog ARFGAP2 (94% identical), rat Arfgap2 (93% identical), mouse Arfgap2 (93% identical), tropical clawed frog arfgap2 (74% identical), zebrafish arfgap2 (72% identical). Paralogues in human: ARFGAP3 (55% identical), ARAP1 (22% identical), ASAP2 (20% identical), ARFGAP1 (20% identical), ARAP3 (19% identical), ARAP2 (19% identical), ASAP1 (18% identical), ASAP3 (16% identical), ACAP3 (14% identical), ACAP1 (13% identical), ACAP2 (13% identical), SMAP1 (13% identical), and 16 more.
Diseases named in the same sentence as ARFGAP2 in open-access papers:
ARFGAP2 is named in the same sentence as 6 diseases in open-access papers, as found by Europe PMC text mining. Sharing a sentence is not in itself a finding about the gene and the disease. The quoted sentences say what the papers report.
adenocarcinoma of the breast (1 paper, 2017). "CELF1 has been found involved in previous fusions with five different partners: with MTCH2 and MYOM1 in SCC and adenocarcinoma of the lung, respectively; with LUZP2 and ARFGAP2 in adenocarcinoma of the breast; and with BBOX1 in grade I-II astrocytoma of the brain." (PMID 28186972, 2017).
Chorea (1 paper, 2021). Chorea (Greek for 'dance') refers to widespread arrhythmic involuntary movements of a forcible, jerky and restless fashion. "Moreover, changes in the regulation of Arf1, such as, for example, those caused by mutations in ARFGAP2 encoding the Arf1 activating protein, manifest in chorea or microcephaly, the symptoms present in ChAc patients and Cohen syndrome patients." (PMID 34830155, 2021).
ARFGAP2 also shares sentences with these, for which no sentence is quoted: adenocarcinoma of the lung (1 paper); astrocytoma of the brain (1); Cohen syndrome (1); microcephaly (1).